TNF (tumor necrosis factor)
Diseases named in the same sentence as TNF in open-access papers (continued):
Sharing a sentence is not in itself a finding about the gene and the disease.
ischemic optic neuropathy (3 papers, 2020 to 2022). "However, overactivated microglia provide excessive amounts of the inflammatory ligands IL-6, IL-1β, and TNF-α, causing ROS, iNOS, NFκB, and NLRP3 inflammatory complex activation; additionally, disruption of neuronal homeostasis was observed in ischemic optic neuropathy." (PMID 34573098, 2021). "Lin and co-authors suggested that AST achieved neuroprotective effects in ischemic optic neuropathy model mice by downregulating both oxidative and inflammatory cascades, as AST administration also reduced the expression of TNFα and IL1β in retinas." (PMID 33014448, 2020).
Large vessel vasculitis (3 papers, 2014 to 2021). A type of vasculitis (inflammation of blood vessel walls) affecting large arteries such as the aorta and branches of the aorta. "IL-1β, IL-6 and TNF-α produced by macrophages amplify the inflammatory response and lead to the large vessel vasculitis which including fever, weakness, anorexia, weight loss and acute phase response." (PMID 34429489, 2021).
Lassa fever (3 papers, 2020 to 2024). A viral hemorrhagic fever that is caused by the Lassa virus, which is transmitted by contact with infected rodents; it is characterized by fever, headache, malaise, myalgia, and hearing loss. "Evaluations of VSV-vectored and MV-vectored Lassa fever vaccines have similarly observed an IFN-γ- and TNF-α-driven effector response post vaccination; IL-2 expression in response to antigen re-exposure was not assessed in these studies." (PMID 33654106, 2021).
lentivirus infection (3 papers, 2016 to 2022). Virus diseases caused by the Lentivirus genus. "At the same time, TNF-α production was significantly down-regulated in DCs after shRNA2 lentivirus infection." (PMID 35967345, 2022). "Furthermore, CD226 shRNA lentivirus infection increased membrane expression of the primary glucose transporter Glut1 whether or not TNF-α was present." (PMID 26910838, 2016).
Leukemia Lymphoid (3 papers, 2012 to 2022). "BIM up-regulation was already shown to be mediated by STAT1 in IL-21-treated lymphocytic leukaemia cells and TNF-α+IFN-γ-exposed β-cells, while CHOP activity is required for BIM up-regulation and apoptosis induction in thapsigargin-treated thymocytes and growth factor-deprived lymphoid precursors." (PMID 22347430, 2012).
lichen sclerosus (3 papers, 2016 to 2024). "Serpin A1 expression is enhanced by the cytokines EGF, TNF-α, INF-γ, and IL-1β in cutaneous SCC cells and the latter three are also upregulated in lichen sclerosus." (PMID 30607583, 2019). "Other studies evidenced an inflammatory response in genital LS; the expression of several pro-inflammatory cytokines, such as IFN-γ, TNF-α, IL-1α and IFN-γ receptor, was increased in specimens of vulval lichen sclerosus from adult women compared with specimens of normal vulva and normal skin." (PMID 27649154, 2016).
Lipoatrophy (3 papers, 2011 to 2021). Localized loss of fat tissue. "Opposing such findings, the literature reports an increase in the expression of IL-6 and TNF-α in PLWHA diagnosed with lipoatrophy." (PMID 34957175, 2021).
localized scleroderma (3 papers, 2021 to 2026). Localized scleroderma is the skin localized form of scleroderma characterized by fibrosis of the skin causing cutaneous plaques or strips. "In summary, this study highlights the significance of IP-10 and TNF-α as potential biomarkers for disease activity in localized scleroderma." (PMID 39337619, 2024). "Collectively, these findings advocate for further translational research to validate and refine the use of IP-10 and TNF-α as biomarkers and therapeutic targets, ultimately aiming to improve patient outcomes in localized scleroderma." (PMID 39337619, 2024). "Treatment of patients with localized scleroderma with vitamin B6 and Xuefu Zhuyu decoction reduced TNF-α and soluble interleukin 2 receptor (sIL-2R) levels in serum, possibly through the improvement of blood circulation and decrease of inflammation." (PMID 34258301, 2021).
long QT syndrome (3 papers, 2016 to 2022). "Therefore, strategies that reduce CCL3 expression in the heart tissue may improve the prognosis of chronic heart diseases associated with TNF-enriched inflammation, as CCC and long QT syndromes." (PMID 32194558, 2020).
lumbar disc degeneration (3 papers, 2022 to 2025). "Inflammatory cytokines, particularly tumor necrosis factor-α (TNF-α) and interleukin-1β (IL-1β), are fundamental contributors to the pathophysiology of lumbar disc degeneration." (PMID 40244065, 2025). "In conclusion, this study preliminarily indicated the relationship between IL-6 and TNF-α and the severity of lumbar disc degeneration." (PMID 35096205, 2022). "Background/Objectives: The aim of the study is to investigate the role of microRNA-17 (miRNA-17), tumor necrosis factor-alpha (TNF-α), and interleukin-6 (IL-6) in the pathogenesis of lumbar degenerative disc disease (LDDD)." (PMID 40095903, 2025).
malignant pleural mesothelioma (3 papers, 2020 to 2022). A malignant neoplasm that arises from mesothelial cells in the pleura and shows a diffuse growth pattern. "Taking malignant pleural mesothelioma (MPM) as an example, even in MPM patients with high levels of TNFα, MPM cell lines assessed were exceedingly resistant to SMs either alone or when incubated in the presence of clinically relevant levels of TNFα." (PMID 32325691, 2020).
mastocytoma (3 papers, 2013 to 2024). A localized tumor composed of sheets of mast cells without atypia. "These two lectins stimulate the production of nitrite and tumor necrosis factor (TNF)-α and inhibit the growth of mouse lymphoblast-like (p815) mastocytoma cells by the production of macrophage-activating factors." (PMID 33171663, 2020).
mastocytosis (3 papers, 2018 to 2023). A clonal myeloproliferative neoplasm characterized by the proliferation and accumulation of neoplastic mast cells in one or multiple organs or organ systems. "A hypothetical model for generation of fatigue in mastocytosis is therefore thatactivated MCs outside the brain release IL-1β, IL-6, TNF-α, and other bioactivemolecules that pass the BBB and activate neuronal cells as well as microglia." (PMID 30350746, 2018).
metabolic acidosis (3 papers, 2018 to 2023). "Macrophages exposed to acidic uremic environment stimulate the production of tumor necrosis factor-α (TNF-α), initiating the acute phase response and leading to an increased concentration of C-reactive protein (CRP), which correlates with metabolic acidosis." (PMID 29324682, 2018).
minimal change disease (3 papers, 2010 to 2024). "It should be noted that there are case reports of children with primary FSGS achieving remissions following treatment with TNFα inhibitors and that TNFα pathway activation is a factor in a subset of FSGS and patients with minimal change disease with poor clinical outcomes." (PMID 39791723, 2024).
monoclonal gammopathy (3 papers, 2024 to 2025). A condition characterized by the abnormal presence of monoclonal immunoglobulins in the blood or urine. "Classical SCLS is most often associated with monoclonal gammopathy, hematologic malignancies, or elevated pro-inflammatory cytokines such as interleukin-2 (IL-2) and tumor necrosis factor-alpha (TNF-α)." (PMID 41281016, 2025). "Their results indicated that MM patients had a reduced T-cell response to complete vaccination and showed less cytotoxic IFN-γ + and TNF-α + CD8 + T cells than monoclonal gammopathy of undetermined significance (MGUS)." (PMID 38720296, 2024). "For instance, pro-inflammatory cytokines such as interleukin-6 (IL-6) and tumor necrosis factor-alpha (TNF-α) promote plasma cell survival and proliferation, potentially contributing to the establishment of monoclonal gammopathy." (PMID 40824475, 2025).
motor neuron disease (3 papers, 2011 to 2023). "A similar effect was observed by Gowing and coll: genetic ablation of TNFα (TNFα gene knock out) does not affect motor neuron disease caused by SOD1 mutations, although higher level of TNFα and of its soluble receptors have been shown in plasma from ALS patients." (PMID 21445241, 2011). "Furthermore, the absence of TNF-α failed to ameliorate motor neuron disease in SOD1 TG mice." (PMID 27070121, 2016).
mucoepidermoid carcinoma (3 papers, 2012 to 2022). A carcinoma morphologically characterized the presence of cuboidal mucous cells, goblet-like mucous cells, squamoid cells, cystic changes, and a fibrotic stromal formation. "Consistent with our data, it has been reported that verproside reduces the TNF-α-induced activity of NF-κB, resulting in suppression of TNF-α-induced MUC5AC expression in pulmonary mucoepidermoid carcinoma cells." (PMID 36670877, 2022). "This prompted us to characterize a cell line derived from mucoepidermoid carcinoma and to correlate metallothionein expression with transforming growth factor-α (TGF-α), tumor necrosis factor-α (TNF-α) and matrix metalloproteinases (MMPs)." (PMID 31936364, 2020). "In this paper, we characterized a cell line derived from mucoepidermoid carcinoma and correlated the expression of metallothionein with transforming growth factor-α (TGF-α), tumor necrosis factor-α (TNF-α) and matrix metalloproteinases (MMPs)." (PMID 31936364, 2020). "Our findings suggest that metallothionein plays an important role in the tumor invasion mechanism in mucoepidermoid carcinoma, through the regulation of proteins directly involved in this process, such as TGF-α, TNF-α and MMP-9." (PMID 31936364, 2020).
multiple system atrophy (3 papers, 2021 to 2024). Multiple system atrophy (MSA) is a neurodegenerative disorder characterized by autonomic failure (cardiovascular and/or urinary), parkinsonism, cerebellar impairment and corticospinal signs with a median survival of 6-9 years. "Other works revealed increased levels of interferon γ, IL-10, IL-18, IL-1β, IL-4, IL-6, transforming growth factor β1, and Tumor Necrosis Factor-α in PSP and Multiple System Atrophy when compared to PD." (PMID 39176092, 2024). "Patients were followed up at 0, 1, 3, and 6 months after treatment, and the Unified Multiple System Atrophy Rating Scale (UMSARS) scores, TNF-α in the peripheral blood, IL-6, percentage of CD4, and CD4/CD8 ratio were evaluated and compared for each follow-up point; any adverse effects were recorded." (PMID 34900026, 2021).
neovascular glaucoma (3 papers, 2020 to 2025). "Among them, the combination strategy of anti- Tumor Necrosis Factor Alpha (anti-TNF-α) agents and anti-VEGF drugs has shown a synergistic effect in neovascular glaucoma." (PMID 40880641, 2025). "Also, in the neovascular glaucoma (NVG) patients, increased level of IL-6, IL-8, PDGF, CCL2, and TNF-α in AH were previously reported." (PMID 32117217, 2020).
neurosyphilis (3 papers, 2024 to 2025). Infection of the brain or spinal cord by Treponema pallidum. "The neuroinflammatory response in neurosyphilis involves the activation of microglia, which release pro-inflammatory cytokines such as tumor necrosis factor-alpha (TNF-α), interleukin-1 beta (IL-1β), and interleukin-6 (IL-6)." (PMID 39728746, 2024).
nocardiosis (3 papers, 2013 to 2021). Nocardiosis is a local (skin, lung, brain) or disseminated (whole body) acute, subacute, or chronic bacterial infection. "More extensive studies of cohorts of patients with different conditions, all treated with anti-TNF, confirmed that the blockade of TNF causes nocardiosis in a percentage of those patients." (PMID 33193422, 2020). "Some patients under treatment with anti-TNF antibodies used to treat Crohn's disease or inflammatory bowel disease to develop nocardiosis as a complication." (PMID 33193422, 2020). "Importantly, the introduction of antitumor necrosis factor (TNF)-α biologics has been shown to increase the incidence of granulomatous infections, including Nocardiosis." (PMID 24171035, 2013). "Although the association of anti-TNF therapy with Nocardiosis has been suggested, none of our patients with Nocardia infection were receiving anti-TNF therapy." (PMID 24171035, 2013).
ocular melanoma (3 papers, 2003 to 2018). A melanoma that arises from the structures of the eye or ocular adnexa. "IHP with melphalan and TNF-α performed in patients with metastases of ocular melanoma or leiomyosarcoma showed overall response rates of 50–52%." (PMID 12610519, 2003).
ocular sarcoidosis (3 papers, 2011 to 2022). A leading cause of inflammatory eye disease is sarcoidosis. "Anti-TNFα agents have shown encouraging results in the treatment of ocular sarcoidosis but further controlled studies are needed to elucidate their role." (PMID 25922606, 2015). "A study that compared the vitreous concentrations of inflammatory cytokines between PDR and ocular sarcoidosis reported that IL-4, IL-17A, IL-31, and TNFα were significantly elevated in PDR, indicating the involvement of Th2 and Th17-related immune responses in the pathogenesis of PDR." (PMID 35806888, 2022).
oral candidiasis (3 papers, 2021 to 2022). Infection of the mucosal lining of the mouth with the fungus Candida albicans. "The ages of participants with oral candidiasis were 64 in the conventional group, 70 and 82 in the anti-TNF-α group and 35 in the anti-integrin-α4β7 group." (PMID 35323234, 2022).
osteopetrosis (3 papers, 2019 to 2024). Osteopetrosis, also known as marble bone disease, is a descriptive term that refers to a group of rare, heritable disorders of the skeleton characterized by increased bone density on radiographs. "Our results demonstrated that TNF overexpression could not compensate for RANKL-mediated osteopetrosis in Tg197/Rankltles/tles mice, supported by the absence of osteoclasts in the bone marrow compartment." (PMID 30804932, 2019). "Notably, TNF overexpression could not compensate for RANKL-mediated osteopetrosis, but promoted osteoclastogenesis between the pannus and bone interface, suggesting RANKL-independent mechanisms of osteoclastogenesis in inflamed joints." (PMID 30804932, 2019).
otosclerosis (3 papers, 2015 to 2023). Formation of spongy bone in the labyrinth capsule which can progress toward the stapes (stapedial fixation) or anteriorly toward the cochlea leading to conductive, sensorineural, or mixed hearing loss. "In the early stages of otosclerosis, the detection of TNF-α correlates with the expression levels of measles virus RNA fragments." (PMID 36923175, 2023). "However, we observed that the TNF-α and IL-1β expression levels were significantly higher in tissue samples obtained from patients with otosclerosis as compared to the control, t (<1.96)." (PMID 24676726, 2015). "Anti-TNF-α agents: TNF-α is an important regulator of bone remodeling, which is abundantly produced in the active phase of otosclerosis." (PMID 36923175, 2023). "However, we cannot completely rule out the potential effect of otosclerosis or any other inflammatory conditions in the subjects in the control group on the levels of TNF-α and hs-CRP." (PMID 36430593, 2022). "In our study, we analyzed the expression level of proinflammatory cytokines (TNF-α, IL-1β), OPG and the presence of measles virus RNA in fragments of the stapes (superstructure and part of the otosclerotic changed footplate) removed during stapedotomy performed in patients with otosclerosis." (PMID 24676726, 2015).
Paralysis (3 papers, 2014 to 2025). Paralysis of voluntary muscles means loss of contraction due to interruption of one or more motor pathways from the brain to the muscle fibers. "Mice that express the human poliovirus receptor and retain normal TNF signaling developed paralysis beginning at 3 days post-infection." (PMID 25365453, 2014).
pelvic inflammatory disease (3 papers, 2020 to 2024). Pelvic inflammatory disease (PID) is an acute or chronic inflammation in the pelvic cavity. "The key target proteins for the SC and PS against pelvic inflammatory disease with dampness-heat stasis syndrome included vascular endothelial growth factor A (VEGFA), von willebrand factor (VWF), interleukin 6 (IL6), tumor necrosis factor (TNF) and nuclear transcription factor 1 (NFκB1)." (PMID 33424592, 2020).
perianal Crohn disease (3 papers, 2025 to 2026). A Crohn disease involving a pathogenic inflammatory response in the anal region. "Anti–tumor necrosis factor therapy has been a mainstay of medical management of perianal Crohn’s disease (CD)." (PMID 40612626, 2025). "Finally, a 40-year-old female with perianal Crohn's disease who was systematically receiving anti-tumor necrosis factor (anti-TNF) treatment was the fourth patient; nonetheless, her transphincteric fistulous tract was not responding to medication and required a seton placement." (PMID 39958108, 2025).
periodic fever syndrome (3 papers, 2018 to 2025). Fevers of unknown etiology recurring over months or years. "It was reported that pre-treatment with IRE1α inhibitor reduced pro-inflammatory cytokines production in tumor necrosis factor (TNF)-receptor-associated periodic fever syndrome (TRAPS) dermal fibroblasts (DFs)." (PMID 30538632, 2018). "Furthermore, in other periodic fever syndromes, such as TRAPS, CAPS and HIDS, IL-1 receptor antagonist anakinra and anti-TNF agents have proven effective in controlling symptoms, whereas colchicine is ineffective in preventing and treating attacks." (PMID 40266382, 2025).
peripheral vascular disease (3 papers, 2014 to 2020). Any disorder affecting blood flow through the veins or arteries outside of the heart. "Pentoxifylline, widely used in peripheral vascular diseases, exhibits complex immunomodulatory effects by influencing the signaling pathways and the production of cytokines such as TNF-alpha, IL-1, TGF-alpha." (PMID 33374706, 2020). "The serum levels of TNF-α, IL-6, and C-reactive protein (CRP) were also higher in subjects with arteriosclerotic peripheral vascular disease compared to healthy controls." (PMID 24766841, 2014).
Periportal fibrosis (3 papers, 2012 to 2014). The presence of fibrosis affecting the interlobular stroma of liver. "The present study showed high levels of IL-5 and TNF-α in individuals with periportal fibrosis." (PMID 23320145, 2012). "High levels of TNF-α produced by PBMC stimulated with Schistosoma antigens or in nonstimulated cells have been found in patients with periportal fibrosis." (PMID 24757288, 2014). "Levels of TNF-α were significantly higher in supernatants from SWAP-stimulated PBMC of subjects with incipient periportal fibrosis (median levels = 1446 pg/mL) than in individuals without fibroses (median levels = 756.1 pg/mL; P = 0.0319)." (PMID 23320145, 2012).
peritoneal adhesion (3 papers, 2012 to 2025). "In this study, we demonstrated that fibrin induced IL-1β, IL-6, TNFα and VEGF-A expression in PMCs, which could be attenuated by QLT-0267, and that QLT-0267 treatment could ameliorate post-surgical peritoneal adhesion." (PMID 29930281, 2018).
photokeratitis (3 papers, 2011 to 2021). Injury to the cornea secondary to ultraviolet light. "In our own prior studies, we demonstrated that fucoxanthin suppresses UVB-induced TNF-α expression and the deterioration of epithelial smoothness in the photokeratitis of corneal tissues." (PMID 34356327, 2021). "The suppressive effects of fucoxanthin on TNF-α and VEGF may be important in avoiding corneal injuries including photokeratitis." (PMID 26751458, 2016).
plasmacytoma (3 papers, 2012 to 2022). Plasmacytoma is a localized mass of neoplastic monoclonal plasma cells that represents approximately 5% of all plasma cell neoplasms. "Other groups' studies have reported that AKBA suppresses VEGF expression in plasmacytoma U266 cells, and inhibits COX−2 mRNA expression induced by TNF in KBM-5 cells." (PMID 22666431, 2012).